NOTCH1 (notch receptor 1)
Diseases named in the same sentence as NOTCH1 in open-access papers (continued):
Sharing a sentence is not in itself a finding about the gene and the disease.
melanoma (continued). "Melanoma cells have increased Notch 1 signaling capable of converting a healthy melanocyte into a melanoma cell in the AKT pathway along with melanoma-inducing hypoxia." (PMID 37102943, 2023). "In vivo, tumors comprised of co-grafted active NOTCH1 overexpressing MAFs and melanoma cells demonstrated smaller volumes, weight and intriguingly, reduced blood vessel densities compared to controls." (PMID 38269089, 2023). "In another study, PI3K/AKT and HIF-1α activated Notch1 signaling under hypoxia during melanoma development." (PMID 36901857, 2023). "A more recent study using mesenchymal stem cell-derived fibroblasts suggests that intracellular Notch1 signaling in CAFs is a molecular switch that controls the plasticity and stemness of melanoma stem/initiating cells." (PMID 36241874, 2022). "NOTCH1 is downregulated in melanoma cell lines with intrinsic and acquired resistance to BRAF inhibition." (PMID 36202798, 2022). "A study has revealed that downregulation of SPAG5 suppresses the ADAM17/NOTCH1 pathway by lowering the expression of FOXM1 in malignant melanoma (MM), thereby dampening the viability, migration, invasion, and EMT of MM cells." (PMID 36118675, 2022). "Stromal fibroblasts, in which the Notch1 pathway is constitutively activated, attenuate melanoma growth and suppress tumor angiogenesis partially by upregulating WISP-1." (PMID 36241874, 2022). "The Notch1-WISP-1 axis controls the regulatory role of stromal fibroblasts in melanoma invasion and metastasis." (PMID 36241874, 2022). "FBXW7 has been found to be mostly inactivated in melanoma that results in constitutive NOTCH1 activation." (PMID 33822486, 2021). "Since WISP-1 is a soluble molecule and is thus easy to be directly administered, our previous findings provide a practicable agent to control melanoma progression using WISP-1 as a functional mediator of Notch1 signaling." (PMID 33705467, 2021). "Based on these findings, it can be said that FBXW7 mutational inactivation represents a potent mechanism for constitutive NOTCH1 activation in melanoma." (PMID 33822486, 2021). "This miRNA is also involved in the development of melanoma by activating Notch1 signaling leading to drug resistance." (PMID 34712602, 2021). "In melanoma cells Notch1 expression correlates with the expression of the stem cell marker CD133, which is regulated by NICD1." (PMID 32796631, 2020). "In another research, inhibition of Notch1 induce anti-melanoma effects via activating both the MAPK and PI3K/Akt pathways." (PMID 32015216, 2020). "In the present study, we further investigated the role of G9a expression in melanoma cells on the Notch1 signaling pathway." (PMID 32015216, 2020). "In sum, these data indicate that G9a can regulate melanoma cell viability, migration and invasion via the Notch1 signaling pathway." (PMID 32015216, 2020). "For example, studies have proven that Notch1 signaling promotes the progression of primary melanoma through activation of mitogen-activated protein kinase/phosphatidylinositol 3-kinase-Akt pathways and upregulation of N-cadherin expression." (PMID 32015216, 2020). "Results from data analysis suggested potential interactions between G9a and Notch1 during melanoma development." (PMID 32015216, 2020). "Notch1 was reported to be overexpressed in melanoma cells thereby driving their metastatic progression." (PMID 32796631, 2020). "In particular, the Notch1 signaling pathway has demonstrated a close relationship with melanoma progression." (PMID 32015216, 2020). "In this study, we further investigated the role of G9a on Notch1 expression and activity in melanoma cells." (PMID 32015216, 2020). "In conclusion, this study was not only helpful for elucidating the role of G9a in melanoma, but also provided data regarding the relationship between G9a and Notch1 signaling in melanoma cells." (PMID 32015216, 2020).
melanoma (continued). "In contrast to Notch1, Notch4 was seen to induce opposite changes in melanoma cells, reexpressing epithelial markers (MET-like changes as explained in the introduction)." (PMID 31934531, 2019). "Elevated levels of the Notch1 receptor have been found during CAF activation, as shown in melanoma, where Notch1-expression negatively influences cancer growth and invasion." (PMID 30917608, 2019). "On the other hand, the absence of Notch1 signaling in CAF leads to an increase in melanoma invasion." (PMID 30917608, 2019). "In both colon cancer and melanoma, honokiol and withaferin A reduce Notch1, Jagged1, and Hes1 expression, inhibiting carcinogenesis." (PMID 30917608, 2019). "Overexpression of Notch1 signaling in stromal fibroblasts has been shown to suppress cell growth via upregulation of WISP1 in melanoma." (PMID 30651114, 2019). "The aim of this study is to investigate the role of Notch1 signaling upon immune suppression induced by melanoma cells." (PMID 29301578, 2018). "Melanoma cell line B16 cells were transfected by lentivirus containing mouse Notch1 gene or Notch1 shRNA to generate B16 cell line that highly or lowly expressed Notch1." (PMID 29301578, 2018). "In the present study, we further evaluated the role of Notch1 expression in melanoma cells on tumor-induced immunosuppression." (PMID 29301578, 2018). "Downregulation or overexpression of Notch1 in B16 melanoma cells inhibited or promoted tumor growth in immunocompetent mice, respectively." (PMID 29301578, 2018). "In the present study, Notch1 expression in melanoma cells upregulated TGF-β1 mRNA expression and promoted TGF-β1 secretion in tumor microenvironment, which enhanced tumor-mediated inhibition of T cell proliferation and activation." (PMID 29301578, 2018). "Notch1 in melanoma tumor promoted more MDSCs and Tregs infiltration in tumor microenvironment and suppressed antitumor immunity." (PMID 29301578, 2018). "Little is known about the role of SPEN, a transcriptional regulator of NOTCH1 and hormone receptor signaling, in melanoma and other cancers." (PMID 30662871, 2018). "Notch1 in anti-tumor immune response was comprehensively appraised in murine B16 melanoma tumor model in immunocompetent and immunodeficient mice." (PMID 29301578, 2018). "Previous studies have demonstrated that Notch1 signaling promoted primary melanoma progression by activating mitogen-activated protein kinase/phosphatidylinositol 3-kinase-Akt pathways and up-regulating N-cadherin expression." (PMID 29301578, 2018). "Notch1 expression in B16 melanoma cells inhibited the infiltration of CD8+ cytotoxic T lymphocytes and NK cells and reduced IFN-γ release in tumor tissue." (PMID 29301578, 2018). "In conclusion, we found that Notch1 signaling in melanoma cells facilitated tumor immune escape and promoted cancer progression via TGF-β1 secretion." (PMID 29301578, 2018). "The role of Notch1 has been proved to be closely related to melanoma progression and become a research hotspot recently." (PMID 29301578, 2018). "Notch-1 promoted melanoma progression by inducing β-catenin, which in turn regulated cyclin D1 expression." (PMID 28977931, 2017). "Recent studies have shown that Andrographolide (Andro), derived from Andrographis paniculata, attenuates tumor growth through abrogation of Notch1-mediated CD133-dependent p38 MAPK activation pathway in CD133+ melanoma cells." (PMID 28137308, 2017). "Our data reveal that WISP-1 is a key downstream mediator of Notch1 signaling in executing the influential role of MSC-DF on melanoma progression." (PMID 27813493, 2016). "We also identified Wnt-induced secreted protein-1 (WISP-1) as a key downstream secretory mediator of Notch1 signaling to execute the influential role of MSC-DF on melanoma metastasis." (PMID 27813493, 2016).
melanoma (continued). "In a skin melanoma mouse model, Liu's group reported that CAF carrying elevated Notch1 activity significantly inhibited melanoma growth and invasion, while CAFs with null Notch1 promoted melanoma invasion." (PMID 27270649, 2016). "This study reveals a selective role of the Notch1—WISP-1 axis in determining the regulatory role of MSC-DF in melanoma metastasis." (PMID 27813493, 2016). "Conversely, the oncogenic effect of Notch1 on primary melanoma cells was mediated by β-catenin, which was upregulated following Notch1 activation." (PMID 26735577, 2016). "We tested the effect of MSC-DF carrying null Notch1 on melanoma growth, invasion and metastasis using an identical co-graft mouse model (n = 8/group)." (PMID 27813493, 2016). "Consistently, co-grafted experimental stromal fibroblasts carrying high Notch1 activity inhibited melanoma growth and angiogenesis in our mouse model." (PMID 27813493, 2016). "In response to MSC-DF carrying varied Notch1 signaling activities, the ability of melanoma cells to form spheroids in co-culture experiments in vitro is consistent with their capability to metastasize in co-graft experiments in vivo." (PMID 27813493, 2016). "Collectively, our results demonstrated that LOF of Notch1 results in MSC-DF promoting melanoma cell migration and spheroid formation, whereas GOF of Notch1 causes MSC-DF to suppress migration and spheroid formation of melanoma cells." (PMID 27813493, 2016). "This is the reason why we used human metastatic C8161 melanoma cells in the current study, which was focused on exploring the role of Notch1 signaling in determining the function of MSC-DF in regulating melanoma metastasis." (PMID 27813493, 2016). "Here, we uncover the Notch1 pathway as a molecular determinant that selectively controls the regulatory role of MSC-DF in melanoma metastasis." (PMID 27813493, 2016). "Overall, our results demonstrate that deletion of Notch1 in CAF enhances their regulatory effect on melanoma invasion." (PMID 26562315, 2015). "In summary, we uncover the Notch1 pathway as a molecular determinant that controls the regulatory role of CAF in melanoma growth and invasion." (PMID 26562315, 2015). "The Notch signaling pathway cross-talks with EGFR/ErbB signaling at the mediator level, e.g. when activated, Notch1 contributes to cell growth and survival via Akt-activation in melanoma." (PMID 25599599, 2015). "To study the role of CAF with null Notch1 in regulating melanoma growth and invasion, we created the 2nd pair of LOFNotch1 vs. LOFctrl mice." (PMID 26562315, 2015). "CAF carrying elevated Notch1 activity significantly inhibited melanoma growth and invasion, while those with a null Notch1 promoted melanoma invasion." (PMID 26562315, 2015). "Here we utilized novel mouse models to explore the role of Notch1 signaling in determining the regulatory role of natural host CAF in melanoma growth and invasion." (PMID 26562315, 2015). "In tumor xenograft mouse models, co-implanted experimental human dermal fibroblasts carrying high Notch1 activity inhibited melanoma growth and angiogenesis, demonstrating that Notch1 activation confers a tumor-suppressive phenotype on experimental CAF." (PMID 26562315, 2015). "NOTCH1 expression is normally decreased in mature melanocytes, whereas melanomas regain expression and activity of NOTCH1." (PMID 24550252, 2014). "The expression of Notch receptors and their downstream target genes is upregulated in primary human melanomas, and the expression of constitutively active Notch1 promotes melanoma progression." (PMID 24527079, 2014). "NOTCH1 is required for melanoma formation, can transform primary human melanocytes and can confer metastatic properties to primary melanoma cells." (PMID 24550252, 2014). "In primary melanoma cells, the activation of Notch1 signaling enables them to gain metastatic capability and the oncogenic effect of Notch1 is β-catenin-dependent." (PMID 24367688, 2013).
melanoma (continued). "Activation of Notch1 signaling induces tumor cell survival in vitro and enhances aggressiveness of vertical growth phase primary melanoma to metastasize in vivo." (PMID 22545195, 2010). "Studies on regulation of MAP2 promoter in melanoma showed that MAP2 is regulated by Notch1 signaling and by neuronal repressor HES1 and activator NeuroD." (PMID 22545195, 2010). "The Notch complex (Notch1–4 receptors and Jagged/Delta ligands) is overactivated in melanoma." (PMID 40806546, 2025). "In addition, overexpression of Notch1 in CAFs inhibits the stemness of tumor cells, while inhibition of Notch1 in CAFs leads to increased expression of stemness markers (Sox2, Oct4, Nanog) in melanoma CSCs." (PMID 40806546, 2025). "Furthermore, Notch1 enhances the proangiogenic properties of melanoma cells that overexpress ALDH1A1, thereby facilitating tumor vascularization and progression." (PMID 40399946, 2025). "Indeed, we show that targeting both Notch1 and ChK1 maximizes the damage leading to mitotic catastrophe and cell death and importantly, significantly increases survival of mice bearing melanoma MBMs." (PMID 40437523, 2025). "Concomitant blockade of both Notch1, via anti-N1, and ChK1, via prexasertib (prex), a ChK1/2 inhibitor currently in several phase 2 clinical trials, exacerbates DNA damage increasing melanoma cell death." (PMID 40437523, 2025). "Inhibiting Notch1 enhanced immunotherapy efficacy in melanoma." (PMID 40574005, 2025). "Anti-Notch1 safely exerts anti-melanoma effects and improves immune checkpoint inhibitor efficacy." (PMID 39491031, 2024). "Of note, most co-occurring mutations in melanoma BRAF Class 2 and 3 (KMT2A, NOTCH1, APC) are of unknown significance, whereas those in Class 1 are amplifications and putative drivers such as NOTCH2 and MET amplifications." (PMID 38275886, 2024). "Moreover, it has been reported that Notch1 increases the expression of the CD133 stemness marker in melanoma cells through the activation of the MAPK pathway." (PMID 39199632, 2024). "In general, melanoma research to date has been clearly focused on the analysis of Notch1." (PMID 38705997, 2024). "Specifically, Notch1-overexpressing CAFs were found to induce a sustained suppression of melanoma cell stemness; conversely, Notch1-silenced CAFs significantly increased the stemness properties of melanoma CSCs by upregulating the expression of the stemness markers Sox2, Oct4 and Nanog." (PMID 39199632, 2024). "Here we show that inhibition of Notch1 by a novel, selective neutralizing monoclonal antibody (anti-N1) developed in our laboratory, delays melanoma growth; promotes an inflamed TME which enhances the efficacy of anti-PD1; and is devoid of the side effects observed with GSI." (PMID 39491031, 2024). "Anti-Notch1 selectively inhibited Notch1 but not Notch2; caused significant melanoma cell death in vitro but did not affect normal melanocytes." (PMID 39491031, 2024). "KAT2A mediates the activation of Notch1 signaling to maintain the stemness features of melanoma." (PMID 37415153, 2023). "However, in murine B16F10 melanoma models with subcutaneous and lung metastases, ectopic over-expression of Notch1 in B16F10 cells accelerated tumor progression and promoted tumor immunosuppression by upregulating TGF-β1." (PMID 37131214, 2023). "Interestingly, overexpression of activated NOTCH1 in MAFs led to reduced proliferation and increased apoptosis of the MAFs in addition to inhibiting growth of melanoma cells in cocultures." (PMID 38269089, 2023).
melanoma (continued). "It was found that MSC‐DF Notch1-/- promoted the formation of spheroids in co-cultured melanoma cells, while MSC‐DFN1IC+/+ (N1IC: Notch1 intracellular domain, an active form of Notch1) suppressed melanoma cell sphere formation capacity, thereby diminished tumor initiation properties." (PMID 37065872, 2023). "KAT2A activates Notch1 transcriptional levels and sustains the stemness feature of melanoma cells." (PMID 37415153, 2023). "Inhibition of NOTCH1 facilitated the efficacy of immunotherapy in melanoma." (PMID 36119057, 2022). "Notch1 (Notch Receptor 1) is critical in modulating melanoma tumor cell growth and survival." (PMID 36119081, 2022). "Other aggressive metastatic melanoma cells may need to be tested over a longer time course in order to assess the effect of increasing Notch1 pathway activity in MAFs on melanoma metastasis." (PMID 33705467, 2021). "In addition, hypoxia induces Akt hyperactivation, which cooperates with HIF1α to promote Notch1 expression, an effector that drives melanoma phenotype switching." (PMID 34604096, 2021). "Our study suggests that targeting melanoma by activating Notch1 signaling in MAFs may represent a novel therapeutic approach." (PMID 33705467, 2021). "In addition, inhibited melanoma growth and angiogenesis in the xenograft model (co-grafted normal skin fibroblasts, pre-engineered to carry high Notch1 activity) reveal that the tumor-promoting effect of stromal fibroblasts is antagonized by Notch activation." (PMID 33705467, 2021). "We utilized Western blot analysis to detect whether G9a is involved in Notch1 activity in melanoma cell lines M14 and A375." (PMID 32015216, 2020). "Moreover, MAPKi-resistant melanoma cells consistently underwent a prominent increase of endogenous NOTCH1 levels and a cell-type dependent increase of the other two miR-204-5p targets RAD51 and FOXM1." (PMID 30254376, 2019). "The Notch1 signaling pathway increases N-cadherin expression in mesenchymal melanoma cells." (PMID 31934531, 2019). "This study was not only important for elucidating the mechanism of tumor-induced immune escape, but also provided a scientific basis for developing novel immunotherapeutic strategies to target Notch1 in B16 melanoma cells to induce innate and adaptive immune responses against tumors." (PMID 29301578, 2018). "The results indicated that Notch1 upregulated tumor-derived TGF-β1 in melanoma cells." (PMID 29301578, 2018). "Inhibition of Notch1 expression in melanoma cells might be considered as a potential therapeutic method for melanoma immunotherapy." (PMID 29301578, 2018). "Our primary study has shown that siRNA-mediated Notch1 knockdown might potentially enhance the effect of IL-2 immunotherapy in malignant melanoma." (PMID 29301578, 2018). "Comparative analyses of common melanocytic nevi, dysplastic nevi, and melanomas have demonstrated an increased expression of Notch1, Notch2, and their ligands, indicating that a positive regulation of these components can be related to the melanoma progression." (PMID 30166456, 2018). "Inhibition of Notch1 decreased the proliferation of melanoma cell line." (PMID 30001383, 2018). "Melanomas re-express Notch1 and depend on the respective signaling for their growth and survival." (PMID 30166456, 2018). "In particular, Notch1 has been considered a primary tumorigenic factor in melanoma." (PMID 30166456, 2018). "Notch1, one of the most canonical substrates of FBXW7 69, was remarkably accumulated in cells upon the loss of FBXW7, and then promoted tumor growth and angiogenesis of melanoma." (PMID 28544818, 2017). "Thus, Aydin and coworkers have found this gene to be mutated in 8% of melanoma patients: FBXW7 mutations determine an inactivation of the encoded protein and a consequent accumulation of its substrate NOTCH1." (PMID 29156643, 2017). "Recent data showed that Notch1 signaling is highly augmented in CD133+ CSCs in melanoma." (PMID 28137308, 2017).